C19orf48P (multidrug resistance-related protein )
Synonyms: C19orf48; CA916798
Gene: Long non-coding RNA gene on chromosome 19 (50,797,687 to 50,804,931, reverse strand). Ensembl gene ENSG00000293495.
Gene Ontology:
Biological process: RNA processing
Cellular component: nucleolus
Diseases named in the same sentence as C19orf48P in open-access papers:
C19orf48P is named in the same sentence as 6 diseases in open-access papers, as found by Europe PMC text mining. Sharing a sentence is not in itself a finding about the gene and the disease. The quoted sentences say what the papers report.
breast carcinoma (1 paper, 2012). "Numerous data have shown that preoperative chemotherapy in breast cancer may induce the expression of many MDR-related proteins, including p-glycoprotein (p-gp), and multidrug resistance-related protein (MRP), amongst others." (PMID 23133636, 2012).
epidermoid carcinoma (1 paper, 2024). "The modulation of apoptotic signaling by Bcl-xS transduction increases the sensitivity of multidrug resistance-related protein-overexpressing epidermoid carcinoma cells to anticancer drugs." (PMID 38473345, 2024).
tumor (3 papers, 2004 to 2023). "Expression of genes for the multiple drug resistance protein (MDR-1), multidrug resistance-related protein (MRP), and lung resistance protein (LRP) may confer the phenotype of resistance to the treatment of neoplasias." (PMID 15543372, 2004).
C19orf48P also shares sentences with these, for which no sentence is quoted: lung carcinoma (3 papers); prostate carcinoma (1); renal carcinoma (1).